MS4A5 (membrane spanning 4-domains A5)
Description:
May be involved in signal transduction as a component of a multimeric receptor complex.
Synonyms: CD20L2; TETM4; CD20-L2
Tractability: Antibody: UniProt predicts a signal peptide or a membrane-spanning region; its Gene Ontology location is reachable by antibodies, with medium confidence.
Gene: Protein-coding gene on chromosome 11 (60,429,572 to 60,455,214, forward strand). Ensembl gene ENSG00000166930.
Subcellular location: Membrane
Gene Ontology:
Biological process: cell surface receptor signaling pathway
Cellular component: plasma membrane; membrane
Genetic constraint (gnomAD): Loss-of-function variants: 10 observed, 14.88 expected, observed/expected ratio (o/e) 0.67, 90% interval 0.41 to 1.14. The upper end of that interval is the gene's LOEUF score, 1.14, which puts it in group 4 of 6, group 1 being the genes least tolerant of losing a copy. Missense variants: 163 observed, 173.01 expected, observed/expected ratio (o/e) 0.94, 90% interval 0.83 to 1.07. Synonymous variants: 71 observed, 62.34 expected, observed/expected ratio (o/e) 1.14, 90% interval 0.94 to 1.39.
Homologues: Orthologues: chimpanzee MS4A5 (99% identical), macaque MS4A5 (94% identical), rabbit MS4A5 (70% identical), rat Ms4a5 (69% identical), mouse Ms4a5 (68% identical), pig MS4A5 (68% identical), dog MS4A5 (66% identical), guinea pig MS4A5 (54% identical), zebrafish ms4a17a.11 (28% identical), zebrafish si:dkey-77f5.10 (26% identical), zebrafish si:ch73-56d11.3 (26% identical), zebrafish ms4a17a.12 (26% identical), and 21 more. Paralogues in human: MS4A1 (24% identical), MS4A4A (24% identical), MS4A6A (24% identical), MS4A12 (23% identical), MS4A7 (22% identical), MS4A14 (21% identical), MS4A3 (21% identical), MS4A15 (20% identical), MS4A18 (20% identical), MS4A2 (20% identical), MS4A8 (20% identical), MS4A13 (18% identical), and 4 more.